CD4 (CD4 molecule)
Diseases named in the same sentence as CD4 in open-access papers (continued):
Sharing a sentence is not in itself a finding about the gene and the disease.
infection (continued). "We also evaluated lung lymphoid cell subsets by characterizing CD4+, CD8+, γδ-TCR+, NK1.1+ T cells, and NK cells, which are involved in the pathophysiology during infection." (PMID 33414457, 2021). "The exogenous expression of human CD4 or CD4/CCR5 in tree shrew lung fibroblasts (TSLFs) also supports HIV-1 entry and efficient infection." (PMID 34076481, 2021). "Specifically, the CD4+/CD8+ ratio is considered a marker for immune state that can be perturbed during inflammation and infection." (PMID 34956180, 2021). "Furthermore, colonic CD4+ iNKT cells undergo a more severe loss than conventional CD4+ T cells in AHI, suggesting that they may be preferentially depleted by HIV-1 during early infection." (PMID 34753817, 2021). "The nonsignificant differences between the proportions of central memory CD4+ T-cells may well become significant at later time points; for example, as a result of contraction of the short-lived effector T-cell subset that is more prominent after infection than vaccination." (PMID 34960185, 2021). "CD4+ and CD8+ T cell responses to PRRSV-2 overall were very low after single infection with PRRSV-2 in either Ctrl or Vac groups." (PMID 34858411, 2021). "Collectively, these results indicated that the IFNAR–/–mice maintained low-level expression of ISGs, produced a severe inflammatory response, and reduced adaptive immune cells (CD4+ T and B cell) in response to SA14-14-2 infection." (PMID 35310394, 2021). "The TCM subset was activated and transformed into TEM cells on the 3rd day after infection in TIGIT+CD8+ T cells and on the 5th day after infection in TIGIT+CD4+ T cells." (PMID 33629951, 2021). "Successful resolution of the infection requires the host to mount an adequate Th1-type immune response characterised by the production of IFN-γ, TNF and IL-2 by CD4+ and CD8+ T cells." (PMID 33524030, 2021). "Following infection, frequencies of both central memory (CD95+ CD28-) CD4+ and CD8+ T cells increased while effector memory (CD95+ CD28-) frequencies declined indicative of antigen driven activation and migration of T cells." (PMID 34494025, 2021). "In the two doses studied here, the difference in the CD4+IFN-γ+ response to Mtb antigens, ESAT-6/CFP-10 and Mtb CW, was the highest at 1-week post-infection and diminished by week 3 post-infection." (PMID 34484203, 2021). "A CD4+/CD8+ ratio between 1.5 and 2.5 is usually considered normal, but heterogeneity according to sex, genetic factors, and infections is observed." (PMID 34288560, 2021). "The current study, based on IHC analysis, revealed that CD3+ T cells (CD4+ and CD8+ T cells) were depleted in SIV-infected macaque brains in the first week of infection, but were replaced by the second week after infection." (PMID 34676832, 2021). "After viral challenge, we found higher frequencies of Granzyme B expressing DP T cells compared to CD4 T cells and, most notably, CD8 T cells at each timepoint post infection." (PMID 34929014, 2021). "While CD4+ and CD8+ T cells are an important source of IFN-γ during the later stages of infection when fully mature granulomas develop to clear infected Kupffer cells, NK and NKT cells were shown to produce IFN-γ during the initial stages of infection." (PMID 34292975, 2021). "Neutralization of IL-2 increased the numbers of recently activated CD4+CD69+ T cells and memory CD4 and CD8 T cells after three weeks of infection and the numbers of splenic T cells producing IFN-γ, TNF-α and IL-10." (PMID 34869064, 2021). "Investigation of effector T cell subsets in lymphatic organs illustrated that groups receiving either of the MP formulations had increased expression in CD4+ and CD8+ T cells that play an important role in combatting virus during infection." (PMID 34835255, 2021). "In a murine model of infection with a mouse-adapted strain of SARS-CoV, depletion of CD4+ T cells resulted in reduced neutralizing antibody responses and delayed virus clearance from the lung." (PMID 34280241, 2021).
infection (continued). "The infection is characterized by sequential expression of viral genes recognized by CD8 and CD4 T cells." (PMID 33679794, 2021). "Percentages of IFN-γ−TNF+IL-2+ double-positive multifunctional CD4 T cells were significantly increased in vaccinated C57BL/6 mice after polyclonal restimulation at weeks 2 and 3 post-infection." (PMID 34351501, 2021). "After vaccination, both CD4 and CD8 T-cell responses are dominated by central memory-like cells, similar to memory T cells generated following natural infection." (PMID 35222312, 2021). "Results showed an increased frequency of TREM-2+CD4+ T cells in the lungs and spleens of C57BL/6 mice after MHV-A59 infection." (PMID 34878838, 2021). "Of note, varied the frequencies of virus-specific CD4+ and CD8+ T cells we detected in patients in this study exhibited similar phenotypes, suggesting that infection produced poor T cell memory." (PMID 33563974, 2021). "Here, we observed significantly increased N-hRSV and bRSV-specific CD4+ T cells and bRSV-specific CD8+ T cells in lung-draining TBLNs near the site of infection, as well as increasing trends in peripheral blood of rBCG-N-hRSV-vaccinated calves at 7 dpi." (PMID 33981309, 2021). "After two weeks of infection with TAS2010, eYFP expression, a proxy for IFN-γ production, was observed exclusively in Thy1.2+ subsets; and 70% of IFN-γ+ cells were CD4+ T cells." (PMID 34695149, 2021). "Fifteen days after znBAZ infection, mice lungs were analyzed for znBAZ colonization of lungs and spleen and IFN-γ-producing CD4+ and CD8+ T cell levels." (PMID 34305935, 2021). "Only when both CD4+ or CD8+ T cells were depleted, mice were unable to clear C. neoformans Δsgl1 and lost complete protection against the WT infection." (PMID 34568097, 2021). "Last, we detected SARS-CoV-2–specific CD4+ and CD8+ T cells after infection and vaccination, and CD4+ T cell activation was robust and appeared indifferent to the S mutations of the B.1.1.7 and B.1.351 variants." (PMID 34035118, 2021). "CD4+ T cells, in particular interferon-γ (IFN-γ)-producing T helper type 1 (Th1) cells, play a central role in host resistance to primary infection with Mtb." (PMID 34351501, 2021). "In order to test for functional resistance towards an infection with HIV, large-scale produced CCR5-edited CD4+-T cells from all runs were simultaneously transduced with GALVenv- and HIVenv-pseudotyped lentiviral vectors and analysed by flow cytometry." (PMID 33867524, 2021). "Circulating CD4+ T-cell responses to most EBV lytic and latent antigens can be detected soon after infection while EBNA1 specific responses are delayed, taking up to six months to develop." (PMID 34882759, 2021). "The absolute events of CD3+CD4+, CD3+CD8+, CD19+, CD3−NK1.1+, and CD3+NK1.1+ cells of PBMCs and splenocytes were lower after infection." (PMID 34566960, 2021). "Lastly, the observational natural infection studies SKI and Immfact provide unique cohorts of subjects to study hallmarks of Bp-specific CD4+ T-cell immunity after recovery from a clinical infection." (PMID 35822011, 2021). "In general, CD69 expression on CD4, CD8 and γδ T-cell populations was higher at the later post-infection timepoints and expression levels agreed with the detection of cytokine production in the corresponding T-cell subsets." (PMID 33627662, 2021). "Recent infection testing algorithm (RITA) integrates more information, such as history of HIV infection, ART information, viral load, CD4 counts, which can reduce the misclassification of recently infected HIV cases and is recommended by WHO guidelines." (PMID 34322472, 2021). "However, immune activation and progression are not a result of the switch to X4 tropism but rather are a consequence of CD4+ T cell activation depleting host target cell availability, driving the target to naïve T cells allowing X4 strains to predominate later in the course of infection." (PMID 35126374, 2021).
infection (continued). "IL-17A production correlated with the expression of Th17 transcription factor ROR gamma t upon the first infection as well as upon the second challenge, while overall frequencies were around 20% higher compared with IL17A+ CD4+ T." (PMID 33595670, 2021). "However, it is possible that any or all of these other types of CD4 T cells may play an important role in infection outcomes, and indeed regulatory T cells have been shown to be important for the development of persistent infection in rodent hosts of different hantaviruses." (PMID 33804381, 2021). "Both CD4+ and CD8+ T cells are elicited following infection and they are effective against secondary influenza virus infections." (PMID 33692193, 2021). "Upregulation of PD-L1 by macrophages and of PD-1 by CD4+, CD8+ T and Tregs IL-10+Foxp3+ upon infection was also observed." (PMID 33776999, 2021). "During chronic infection, including infections with HCMV, MCMV, herpes simplex virus, varicella zoster virus, murine gammaherpesvirus 68, and Epstein–Barr virus, CD4 + T cells play a direct antiviral role, inhibiting virus lysis and replication." (PMID 34950144, 2021). "Informed by the protective immunity observed after natural infection, vaccine approaches that elicit antiviral SARS-CoV-2-specific CD4+ and CD8+ T cells in coordination with neutralizing antibodies generate more robust and durable protective immunity." (PMID 34728796, 2021). "At the level of the trigeminal ganglion, several groups have shown infiltration of CD8+ T cells after primary infection in both humans and mice, and have demonstrated that in mice these CD8+ T cells synergise with CD4+ T cells to control HSV-1 reactivation." (PMID 33668777, 2021). "In a separate study, IL-21 secretion by CD4+ T cells was noted to support CD8+ cytotoxic T cell responses in chronic progressors, even during the late-stage infection, leading to diminished virus replication." (PMID 34721397, 2021). "Overall, we conclude that although we detect fewer antigen-specific CD8+ than CD4+ T cells to SARS-CoV-2, they persist 6.1 mo after infection." (PMID 33533915, 2021). "We observed BAL cells expressing the activation marker CD44 and surface markers specific for T lymphocytes (CD4 and CD8) on day 7 post-infection." (PMID 34359982, 2021). "CD4+ T cells from individuals in the early HIV infection stage were enriched in genes involved in metabolic and infection-related pathways, whereas CD8+ T cells were enriched in genes involved in cell cycle and DNA replication." (PMID 34603402, 2021). "Therefore, based on this initial infection process, the inhibitors that block the attachment or fusion process are collectively termed “entry inhibitors” and can act on the glycoproteins (gp120 and gp41), and receptors and coreceptors present on the host cell surface (CD4 and CCR5 or CXCR4)." (PMID 34577593, 2021). "Mice that were vaccinated with either the streptococcal vaccine Strep‐vax or Multi‐vax had significantly elevated levels of CD4+ T cells, CD69+ activated CD4+ T cells and CD8+ T cells following super‐infection compared to unvaccinated mice." (PMID 34527244, 2021). "After 30 days, CD4+ T-cells in blood and spleen expressed significantly higher levels of CD25 compared to controls, which remained high up to 60 days of infection." (PMID 34685494, 2021). "Another cytokine that demonstrates robust levels from an early infection stage is CXCL9, responsible for CD4+ lymphocyte recruitment." (PMID 33746980, 2021). "To compare priming of CD4+ T cells to VACV and BCG using the same tool, we engineered rVACV-Ag85B, and used P25 TCRTg cells to gauge T cell priming in the dLN after footpad infection." (PMID 33419767, 2021). "Further exploration is yet required to decode precise roles of CD4+ and CD8+ T cells against acute SARS-CoV-2 infection as well as in protection from future infection." (PMID 34276652, 2021).
infection (continued). "Early infection with VHSV has been shown to increase transcription levels of some genes in the liver of rainbow trout, namely CD3 and CD4, while CD4 and CD8 were seen to be increased in olive flounder." (PMID 34068522, 2021). "However, improvements in MHC tetramer technology have enabled the detection of rare cells, and shown for instance that the precursor of antiviral CD4+ T cells may acquire a memory phenotype through cross-recognition of environmental or self antigens, thus priming CD4+ T cells for future infections." (PMID 33430234, 2021). "Intracellular cytokine-staining analyses also showed significant reduction of IFN-γ- and IL-17-producing CD4+ and CD8+ T cells in both spleen and lung of the SND1-/- mice after infection." (PMID 33635920, 2021). "On day 8 post LCMV-Armstrong infection, Mettl3fl/flCd4-Cre mice-derived CD4+ T cells had much lower cell numbers of CD44+CXCR5+ TFH cells than those of competitor bone marrow-derived CD4+ T cells." (PMID 33637761, 2021). "We observed greater numbers of cytokine-producing virus-specific CD4+ and CD8+ T cells in Selplg-/- mice at both the effector and memory stages after infection." (PMID 34326837, 2021). "Although activated T CD4/CD8 cells are the main target cells of the virus, both the location and function of macrophages make it possible to generate a continuous infection of T cells through continuous cell–cell interactions." (PMID 34445073, 2021). "Using multicolor fluorescence microscopy we were able to measure recruitment of B cells (CD19+), CD4+ cells, and CD8+ T cells to the liver following AAV8 infection." (PMID 33376758, 2021). "Furthermore, considering the key role of CM CD4 T-cells in maintaining homeostasis of the overall CD4 T-cell compartment, the higher levels of CM T-cells infection we described in ISR may prevent adequate repopulation of all CD4 memory cells despite higher cytokine levels." (PMID 34449812, 2021). "After 30 days of infection, enriched CFSE-labeled CD4+ T cells (2 × 106) from M.tb-infected CD45.1 mice were injected intravenously into TCRβ−/− mice and C57Bl/6 WT control mice." (PMID 34899731, 2021). "IL-10 has a central role in limiting inflammation and inhibiting CD4+ T cell-mediated severe immunopathology, and IL-4 functions to enhance IFN-γ production in the late stage of infection." (PMID 33087183, 2021). "After infection, infiltrated cells included NK cells, NKT-like cells, CD4+ and CD8+ T lymphocytes and dendritic cells (cDC2), in BAL of Air mice at 12 dpi." (PMID 34944654, 2021). "Specifically, HIV-1 targets CD4 T cells with increased OXPHOS and glycolysis in an in vitro infection system, likely due to reduced metabolism that inhibits HIV-1 replication." (PMID 34017335, 2021). "CD3+CD4+ ATL cells were completely lysed (depleted to ~0%) by AAV-CD4CAR 48 h post-infection, while AAV-CD20CAR was unable to lyse CD3+CD4+ ATL cells." (PMID 34162832, 2021). "CD4+ helper T cells and CD8+ cytotoxic T cells were also shown to increase in presence within 1 week post-SE infection and vaccination in the intestine, as compared to uninfected and non-vaccinated chickens." (PMID 34404469, 2021). "On the 3rd and 7th days post infection, the TCM subset of T. gondii-specific TIGIT+CD4+ T cells in the spleen was activated and transformed into TEM cells." (PMID 33629951, 2021). "At 17 weeks post SHIVSF162P3CN infection, 2 and 3 out of the 4 macaques in group A had CD8+ and CD4+ T cells that recognised epitopes identified during the vaccination phase, respectively." (PMID 34125864, 2021). "In both donors, we identified CD4+ and CD8+ T-cell clones with transient clonal expansion after infection." (PMID 33399535, 2021). "On day zero post-infection, tamoxifen significantly decreased CD3+, CD3+/CD4+, CD3+/CD8+ and B220+ cells compared with both control groups." (PMID 34204678, 2021).
infection (continued). "(G–L) Flow cytometry analysis of CD4 T cell (G), CD4/CD8 T cell ratio (H), γδ T cell (I), neutrophil (J), Ly6Chi cell (K), and CD64+ MerTK+ cell (L) on day 8 post (PFU 7e2) infection." (PMID 34151773, 2021). "Nc-Spain1H infection induced higher IL4 levels in stimulated blood and a higher CD4+/CD8+ ratio in PBMC." (PMID 34239816, 2021). "Abrogation of PMCA4 did not significantly alter the numbers of activated (antigen-experienced) CD4+ and CD8+ T cells (as defined by upregulation and co-expression of CD11a and CD49d;) in the spleen on day 7 of infection." (PMID 34215257, 2021). "As previously shown by trans infection of total CD4+ T cells, B cell-mediated trans infection of both TN and TCM was significantly more productive than DC-mediated trans infection of either subset (one-way ANOVA, P < 0.0001)." (PMID 33688006, 2021). "Remodeling of CD4+ T cells by HIV includes downregulation of cell-surface CD4 and CD28 and upregulation of select homing receptors upon infection." (PMID 33910003, 2021). "The percentage of CD4+ T cells in the HLN from the early stage (trial 1 and trial 2) and late stage of the infection (trial 2) were analysed by flow cytometry." (PMID 34215335, 2021). "Within the CD3+ T cell compartment, both CD4+ and CD8+ T cells accumulated at the site of infection in absolute numbers." (PMID 34299148, 2021). "GS-9620 showed antiviral activity in ex vivo HIV-1 infected PBMCs when pre-stimulated for 48 hours with GS-9620 prior to infection, however GS-9620 was inactive against HIV-1 in purified CD4+ T cells." (PMID 34630386, 2021). "We found that IL-17-producing pathogen-specific CD4 TRM cells accumulate in the nasal tissue during infection with B. pertussis and these TRM cells expanded locally following re-infection with B. pertussis." (PMID 33976385, 2021). "This means that while infection with TMEV induces a decrease in naïve and central memory cell populations in young mice, effector memory CD4 T cells were significantly increased." (PMID 34355492, 2021). "It is well known that CD4+ memory T cells are major target cells for HIV/SIV, leading to massive CD4+ memory T-cell infection and subsequent depletion quite early in infection." (PMID 34960667, 2021). "After polyclonal restimulation, frequencies of IFN-γ+TNF+IL-2+ triple-positive multifunctional CD4 T cells were enhanced in vaccinated C57BL/6 mice when compared to the unvaccinated C57BL/6 animals at weeks 2 and 6 post-infection." (PMID 34351501, 2021). "When CD4+ T cells were depleted from macaques infected with SHIV, the infection was independently sustained by macrophages." (PMID 33897659, 2021). "All CD4+-T cells already present in the patient would potentially become HIV targets, which might create new HIV reservoirs and impends the loss of large parts of the acquired adaptive immunity thus conferring high infection risks, which is particularly problematic for HIV patients." (PMID 33867524, 2021). "Upon analysis of the lung at 14 days post-infection, activation markers CD11a and CD44 were both upregulated on polyclonal CD4+ T cells." (PMID 34237106, 2021). "On the other hand, various studies have confirmed that productive infection of HIV in primary hepatocytes and hepatoma cell lines is CD4-independent." (PMID 33669403, 2021). "Virus-specific CD4+ T cells have also been shown to display an exhausted phenotype similar to exhausted, CD8+ T cells, which appears to occur early during LCMV Cl 13 infection." (PMID 34696381, 2021). "We obtained peripheral blood resting CD4+ T-cell subsets (NV, SCM, CM, TM, EM, and TD) from large blood draws in 11 participants, 6 who initiated ART <6 months after infection (early group) and 5 who initiated ART >6 months after infection (late group)." (PMID 34544282, 2021). "As observed for day 1 post infection, in the SIM group we observed increased percentage of multifunctional effector CD4 T cells expressing IFNγ/TNFα or IL-17/TNFα." (PMID 34925371, 2021).